LINC02328 (long independently transcribed non-coding RNA 2328)
Gene: Long non-coding RNA gene on chromosome 14 (85,911,438 to 86,161,539, forward strand). Ensembl gene ENSG00000258733.
Diseases named in the same sentence as LINC02328 in open-access papers:
LINC02328 is named in the same sentence as 1 disease in open-access papers, as found by Europe PMC text mining. Sharing a sentence is not in itself a finding about the gene and the disease. The quoted sentences say what the papers report.
tumor (1 paper, 2023). "LINC00944, LINC02611, PRKAR1B-AS1, LINC02328 and LINC02100 were expressed at higher levels in ccRCC tumor tissues compared to that in normal tissues, which was consistent with the results of the TCGA-ccRCC cohort." (PMID 37415739, 2023).